TF (transferrin)
Diseases named in the same sentence as TF in open-access papers (continued):
Sharing a sentence is not in itself a finding about the gene and the disease.
Cognitive impairment (10 papers, 2013 to 2024). Abnormal cognition is characterized by deficits in thinking, reasoning, or remembering. "Therefore, our study aimed to better understand the association between transferrin gene polymorphism, cognitive deficits, and psychiatric symptoms in a large sample of chronic schizophrenia patients." (PMID 36362642, 2022). "Interestingly, Trf, encoding transferrin for iron transport was upregulated in oligodendrocytes, suggesting a possible involvement of Trf on the described association between iron deposition and cognitive deficits in mTBI34,35." (PMID 30254269, 2018). "In this study, we compared the levels of transferrin in plasma among individuals with normal cognition (NC), individuals with mild cognitive impairment (MCI), and patients with mild AD dementia from the Alzheimer’s Disease Neuroimaging Initiative (ADNI) cohort." (PMID 32226377, 2020). "To gain insights on iron-dependent processes in cognitive impairment, we extended the analyses to further SNPs: FPN1 -8CG, HAMP -582AG and TF P570S." (PMID 29518107, 2018). "Some authors suggested that the combination of TF C2 and HFE C282Y can lead to an excess of redox-active iron even in mild cognitive impairment (MCI)." (PMID 23935582, 2013). "Its inclusion in future analysis should be considered, as R2* values in some DGM regions have been described to be correlated with serum transferrin in older subjects with no cognitive impairment." (PMID 39498389, 2024). "With the collaboration of Pep63, PA, and transferrin, Tf-Pep63-Lip was proven to bypass the BBB into the brain and could rescue cognitive impairment in AD mice." (PMID 34548476, 2021).
endothelial dysfunction (10 papers, 2008 to 2025). In vascular diseases, endothelial dysfunction is a systemic pathological state of the endothelium (the inner lining of blood vessels) and can be broadly defined as an imbalance between vasodilating and vasoconstricting substances produced by (or acting on) the endothelium. "Increased TF levels have been related to an increased risk of cardiac events because induction of TF is highly correlated with thrombogenesis and endothelial dysfunction." (PMID 19055790, 2008). "Deregulated complement activation drives inflammation by enhancing neutrophil activation and recruitment to the infected lungs, and by promoting TF expression, leading to microvascular thrombosis and endothelial dysfunction." (PMID 35163743, 2022). "Activation of TF, the extrinsic coagulation pathway, in association with impaired fibrinolysis via PAI-1 activation suggests that UfCPs exposure induces endothelial dysfunction and activates the coagulatory pathway, both of which are correlated with overall cardiovascular risk." (PMID 19055790, 2008). "Vice versa, posttranscriptional control of vascular TF expression by miR-181b represents a potential avenue to improve endothelial dysfunction and thrombosis risk without facing bleeding issues as observed by direct inhibition of inflammatory coagulation factors." (PMID 32066445, 2020). "The observed pro-atherosclerotic effect in these mice was attributed to the occurrence of increased levels of non-transferrin-bound iron (NTBI) promoting lipid peroxidation and endothelial dysfunction." (PMID 38727367, 2024).
Hepatitis (10 papers, 2008 to 2023). Inflammation of the liver. "The presence of very high transferrin saturation can pose a diagnostic dilemma in the setting of new-onset hepatitis." (PMID 24024049, 2013). "Because similar changes were observed in hepatitis, we can conclude that the serum profile of transferrin isoforms is involved in the pathogenesis of the disease." (PMID 35329964, 2022). "Thus, we can conclude that the change in transferrin isoform profile in pancreatitis is only similar to that seen in hepatitis." (PMID 35329964, 2022). "Depletion of Treg in TF-OVAxDEREG mice dramatically amplified T cell-mediated hepatitis." (PMID 26599014, 2015). "No significant increase in ALT-levels was observed after transfer of 4 million naïve or effector OT-II T-cells into TF-OVA mice, demonstrating that neither naïve nor effector CD4 T-cells are sufficient to induce hepatitis." (PMID 21779338, 2011).
metastatic disease (10 papers, 2015 to 2025). "A positive association of PhA with nutritional status, BMI, fat-free mass, and serum albumin and transferrin levels has been shown in studies involving cancer patients with advanced disease (metastatic disease)." (PMID 39205363, 2024). "Tumor TF expression has been correlated to increased risk of VTE and metastatic disease, indicating that TF has direct clinical implications both in tumor progression and VTE development." (PMID 30412630, 2018). "Given the conservation of CD and transferrin up-regulation in metastatic tumors, the strategy might be a common metastatic mechanism." (PMID 39810853, 2025). "Nitori and colleagues suggested that TF may have prognostic significance in PDAC: “high TF” patients presented with larger tumors and more advanced metastatic disease with TF prominently expressed at the invasive front of the primary tumor." (PMID 38473827, 2024). "Thus, in metastatic tumor nature both angiogenesis and TF-dependent coagulation processes collaborate as perfect match ‘soulmates’." (PMID 37626742, 2023).
atransferrinemia (9 papers, 2015 to 2026). "Aceruloplasminemia and atransferrinemia are rare disorders caused by deficiencies in ceruloplasmin or transferrin, respectively." (PMID 30420953, 2018). "Because atransferrinemia/hypotransferrinemia is caused by recessive mutations in the Tf gene resulting in iron-deficient hypochromic anemia in humans and mice, reduced expression of TF may cause hypoferremia." (PMID 26527688, 2015). "Congenital atransferrinemia (OMIM #209300) is a rare, early onset recessive disorder caused by transferrin deficiency (< 20 mg/dl) due to mutations in the transferrin-encoding TF gene on chromosome 3q22.1." (PMID 30420953, 2018). "Its physiological importance is underscored by atransferrinemia, a rare disorder in which individuals lacking plasma transferrin nonetheless retain the capacity to distribute dietary iron to essential organs, implying the presence of compensatory iron transport routes." (PMID 41997899, 2026).
congenital disorder of glycosylation (9 papers, 2018 to 2025). Congenital disorder of glycosylation (CDG) is a fast growing group of inborn errors of metabolism characterized by defective activity of enzymes that participate in glycosylation (modification of proteins and other macromolecules by adding and processing of oligosaccharide side chains). "CG is considered a secondary congenital disorder of glycosylation (CDG), and CG patients can have altered transferrin mobility in diagnostic tests because the transferrin protein is improperly glycosylated." (PMID 38974607, 2024). "These patients also showed deficient transferrin (TF) glycosylation with a Type 2 congenital disorder of glycosylation (CDG) pattern." (PMID 29321044, 2018). "Diagnosis of PMM2-CDG, the most common congenital disorder of glycosylation (CDG), relies on measuring carbohydrate-deficient transferrin (CDT) and genetic testing." (PMID 38587076, 2024). "Deficiency of asparagine-linked glycosylation 13 (ALG13) causes a congenital disorder of glycosylation (CDG), usually with normal transferrin electrophoresis and consisting of a DEE." (PMID 38612920, 2024). "Availability of DBS for the mass spectrometric analysis of the diagnostic marker proteins, transferrin (Tf) and apolipoprotein CIII (apoCIII), of congenital disorders of glycosylation (CDG) was examined." (PMID 36713804, 2022). "Transferrin is a clinically validated biomarker of congenital glycosylation disorders." (PMID 39081747, 2024). "Neither class of DHDDS variants exhibit a serum transferrin glycosylation defect that is the hallmark of many forms of congenital disorder of glycosylation (CDG)." (PMID 37443173, 2023). "Here we present a rare case of a young female patient with symptoms of ADHD and an extremely high carbohydrate-deficient transferrin (CDT) of 19,6% (< 1,3%) indicating the presence of a congenital disorder of glycosylation (CDG)." (PMID 40301838, 2025).
endometrial cancer (9 papers, 2010 to 2024). Primary or metastatic malignant neoplasm involving the endometrium (mucous membrane that lines the endometrial cavity). "Another study suggested that the panel of ApoA-I, TTR, and TF distinguished normal samples from early-stage endometrial cancer with a sensitivity of 71% (specificity, 88%) and normal samples from late stage endometrial cancer with a sensitivity of 82%." (PMID 31035965, 2019). "For instance, transferrin, prealbumin and apolipoprotein-1 combined enable the early detection of endometrial cancer with a sensitivity and specificity of 71% and 88%, and detection of late stage disease with a sensitivity of 82% and a specificity of 86%, respectively." (PMID 32429365, 2020). "Last but not least, our data on the principal role of EGFR in TF expression are consistent with corresponding studies of other designs in glioma, epidermoid, colorectal, breast and endometrial cancer cells." (PMID 34205482, 2021). "We found all endometrial carcinomas that showed high TF expression, regardless of their high or low HER2/neu expression, were highly susceptible to IDCC in the presence of effector cells." (PMID 21693061, 2011).
fibrosis (9 papers, 2015 to 2025). the formation of excess fibrous connective tissue in an organ or tissue in a reparative or reactive process. "A recent study demonstrated a significant decrease in serum transferrin levels in advanced fibrosis than in mild fibrosis." (PMID 28439208, 2016). "Serum iron, transferrin saturation and ferritin positively correlated with age, ALT, GGT, bilirubin and hemoglobin concentration as well as fibrosis stage and degree of hepatocyte iron deposits in liver biopsy samples." (PMID 27125837, 2017).
Infertility (9 papers, 2022 to 2024). "Women with unexplained infertility demonstrated a lower transferrin saturation (median 17.3%, IQR 12.7-25.2 versus 23.9%, IQR 15.4-31.6; p= 0.034) and a lower mean corpuscular hemoglobin concentration (median 33.6 g/dL, IQR 33.0-34.1 versus 34.1 g/dL, IQR 33.2-34.7; p= 0.012)." (PMID 37361544, 2023). "In contrast, women with unexplained infertility demonstrated a lower transferrin saturation (median 17.3%, IQR 12.7-25.2 versus 23.9%, IQR 15.4-31.6; p= 0.034), a lower mean corpuscular hemoglobin concentration (median 33.6 g/dL, IQR 33.0-34.1 versus 34.1 g/dL, IQR 33.2-34.7; p= 0.012)." (PMID 37361544, 2023).
lupus (9 papers, 2012 to 2026). "Ferritin and transferrin saturation should be monitored before each dose, particularly in high-risk patients, such as those with systemic lupus erythematosus or recent blood loss." (PMID 41517670, 2026). "TF expression is obviously one among many mechanisms responsible for procoagulation state in lupus." (PMID 32197340, 2020). "In patients with lupus, AGP and CRP increase whereas transferrin decreases." (PMID 31766160, 2019).
renal failure (9 papers, 2005 to 2026). "Further, the most differentially abundant proteins found to be associated with renal failure were serotransferrin (TF), alpha-trypsin 1 (SERPINA1), alpha-1B-glycoprotein (A1BG), and NHL repeat-containing protein 3 (NHLRC3)." (PMID 38536893, 2024). "The findings included a pathological urinary sediment, increased excretion of albumin and/or transferrin and/or glomerular antigens, and in three of them renal failure was also more prevalent." (PMID 16354301, 2005). "Urine transferrin correlated with subclinical atherogenesis in patients with t2DM without renal failure, suggesting its potential to identify cardiovascular risk in patients at very early nephropathy stage without microalbuminuria." (PMID 34743740, 2021). "Inflammation is recognized as increase in concentration of positive acute phase proteins such as CRP (reaching as high as 5-10 mg/dL in renal failure) and decrease in negative acute phase proteins such as albumin and transferrin." (PMID 28487874, 2017).
alcoholic liver diseases (8 papers, 2014 to 2024). A disorder caused by damage to the liver parenchyma due to alcohol consumption. "Abnormal glycan structures of liver‐derived proteins such as transferrin (TF) and haptoglobin have been described in alcoholic liver disease, nonalcoholic steatohepatitis and primary sclerosing cholangitis." (PMID 32557671, 2020). "The most important alterations observed in alcoholic liver disease are desialylation of transferrin and also haptoglobin, alpha 1-antitrypsin, and ceruloplasmin." (PMID 24959592, 2014).
cardiomyopathy (8 papers, 2011 to 2025). A disease of the heart muscle or myocardium proper. "In view of the clinical symptoms of multiorgan involvement with seizures, cardiomyopathy, eye, and liver abnormalities as well as thrombocytopenia and ATIII deficiency, a CDG was suspected and TIEF and ESI‐MS of serum transferrin were performed." (PMID 31741824, 2019).
cognitive decline (8 papers, 2019 to 2025). "In conclusion, higher plasma transferrin levels were associated with a steeper cognitive decline in patients with MCI and AD." (PMID 32226377, 2020). "Third, the causal association between plasma transferrin and cognitive decline cannot be determined due to the study design." (PMID 32226377, 2020). "In the longitudinal study, the finding that higher plasma transferrin levels at baseline were associated with a steeper cognitive decline in older individuals with MCI and AD is novel." (PMID 32226377, 2020). "Thus, the association between the plasma transferrin levels and cognitive decline in the NC group will need further investigation." (PMID 32226377, 2020). "First, in the longitudinal study, we did not observe an association between plasma transferrin and cognitive decline in the NC group." (PMID 32226377, 2020). "Third, in the longitudinal analyses, we found that a higher plasma transferrin was associated with a steeper cognitive decline in the MCI and AD groups, but not in the CN group." (PMID 32226377, 2020). "Collectively, these data strengthen the notion that the dysregulation of iron metabolism might contribute to the pathogenesis of AD, and lowering the levels of plasma transferrin should be considered as a therapeutic strategy to slow the cognitive decline in MCI and AD patients." (PMID 32226377, 2020). "Finally, in the longitudinal study, we found that a higher plasma transferrin was associated with a steeper cognitive decline in the MCI and AD groups, but not in the NC group." (PMID 32226377, 2020).
colitis (8 papers, 2019 to 2025). Inflammation of the colon. "In the DSS colitis model, weight loss in mouse group with transferrin overexpression was lower than that in the control and transferrin knockdown group." (PMID 38274126, 2024). "A dietary intake of a 0.05% α-TF or 0.05% γ-TF-rich mixture inhibited the colitis-associated elevation of pro-inflammatory IL-6 in the colon." (PMID 33919211, 2021). "In the TCRαKO colitis model, alleviation of inflammation-associated histological changes was observed in transferrin overexpression mice compared with the control and transferrin knockdown mice." (PMID 38274126, 2024). "Mouse colitis models show that transferrin shortage impairs host’s tolerogenic responses, while its supplementation promotes immunotolerance." (PMID 38274126, 2024). "The immunosuppressive function of transferrin was further demonstrated by mouse colitis models induced by DSS and TCRαKO and monkey with spontaneous chronic colitis, which are widely used to study IBD, immune imbalance, and intestinal dysbiosis." (PMID 38274126, 2024). "Peroxiredoxin 2 (PRDX2) was transiently increased during mild colitis development, whereas transferrin (TF) was only increased later in severe colitis mice." (PMID 30774653, 2019). "Importantly, TC6 blocked transferrin’s improvement on disease activity index and inhibition on colon length shortening in the colitis model." (PMID 38274126, 2024). "Transferrin down-regulation impaired host tolerogenic responses by dysregulating DC, Tregs, and Bregs homeostasis in the gut while its overexpression or exogenous administration of transferrin showed protective effects by suppressing the inflammatory response to repair colitis." (PMID 38274126, 2024). "The blood routine parameters, including RBC, HCT, HGB, MCV, and MCH, as well as serum iron, UIBC, TIBC, and TF levels, were assessed to evaluate the impact of DSS-induced colitis and the effects of preventive EGCG supplementation." (PMID 39940407, 2025). "This study aimed to evaluate the abilities of two peptides derived from egg albumin transferrin, IRW and IQW, to treat enteritis in a mouse model of Citrobacter rodentium-induced colitis by evaluating serum metabolomics and gut microbes." (PMID 31001226, 2019). "Interestingly, preventive supplementation with EGCG showed a restorative effect on RBC count, HCT, HGB, serum iron, UIBC, and TF levels, demonstrating the potential of EGCG in mitigating the hematological disturbances induced by DSS-induced colitis." (PMID 39940407, 2025).
fatty liver disease (8 papers, 2020 to 2025). A reversible condition wherein large vacuoles of triglyceride fat accumulate in liver cells via the process of steatosis. "Exclusions were subjects with elevated transferrin level, chronic hepatitis B or C, excessive alcohol use, or prescription medications that might cause hepatic steatosis." (PMID 34926533, 2021).
glaucoma (8 papers, 2014 to 2026). Increased pressure in the eyeball due to obstruction of the outflow of aqueous humor. "In the aqueous humor, TF and hepcidin levels were increased in primary open-angle glaucoma (POAG) eyes as compared to control eyes undergoing cataract surgery, suggesting a deregulation of iron homeostasis in glaucomatous conditions." (PMID 36361544, 2022). "Herein, we have investigated the neuroprotective potential of TF in various experimental conditions mimicking pathways involved in glaucoma neuropathy, including excitotoxicity, hypoxia, and iron intoxication, using ex vivo organotypic rat retinal explants." (PMID 36361544, 2022). "Mutations in the gene that are associated to glaucoma and the knockdown of OPTN in HeLa cells have been demonstrated to cause the disruption of TF uptake and TF/TFRC endosomal recycling, suggesting a crucial role of the autophagy receptor also in cellular iron homeostasis." (PMID 39684697, 2024). "This suggests that the neuroprotective role of TF could be extended to different types of glaucoma including normotensive and hypertensive forms." (PMID 36361544, 2022). "Likewise, an increased immunoreactivity of these autoantibodies, except transferrin, has been described for patients suffering from glaucoma, indicating the close analogy of this experimental animal model to glaucoma." (PMID 27090083, 2016). "To determine the potential neuroprotective role of TF against RGC degeneration in vivo, we investigated its effect in a validated animal model for glaucoma: the microbead occlusion model in rats." (PMID 36361544, 2022). "For glaucoma, PTGDS, GSTP1, SPD1, and CST3 were expressed significantly higher in almost all tissues; CRP, ALB, and TTR were markedly increased in the liver; MBP and TF exhibited high expression in the brain." (PMID 37052519, 2023).